SLC33A2 (solute carrier family 33 member 2)
Synonyms: MFSD3
Tractability: Antibody: UniProt predicts a signal peptide or a membrane-spanning region. PROTAC: ubiquitination databases record sites on it.
Gene: Protein-coding gene on chromosome 8 (144,509,070 to 144,511,213, forward strand). Ensembl gene ENSG00000167700.
Subcellular location: Cell membrane
Subcellular location (Human Protein Atlas): Vesicles
Gene Ontology:
Molecular function: protein binding; transmembrane transporter activity
Biological process: transmembrane transport
Cellular component: membrane; plasma membrane
Genetic constraint (gnomAD): Loss-of-function variants: 37 observed, 26.74 expected, observed/expected ratio (o/e) 1.38, 90% interval 1.06 to 1.79. The synonymous counts are far from expectation, so gnomAD's model fits this gene poorly and the ratio says little. Missense variants: 695 observed, 456.5 expected, observed/expected ratio (o/e) 1.52, 90% interval 1.43 to 1.62. Synonymous variants: 373 observed, 234.8 expected, observed/expected ratio (o/e) 1.59, 90% interval 1.46 to 1.73.
Homologues: Orthologues: chimpanzee MFSD3 (99% identical), pig MFSD3 (80% identical), mouse Mfsd3 (78% identical), rat Mfsd3 (78% identical), guinea pig MFSD3 (77% identical), dog MFSD3 (75% identical), zebrafish mfsd3 (47% identical), tropical clawed frog mfsd3 (45% identical), Drosophila melanogaster CG9706 (22% identical), Caenorhabditis elegans T26C5.3 (21% identical). Paralogues in human: SLC33A1 (24% identical).
Diseases named in the same sentence as SLC33A2 in open-access papers:
SLC33A2 is named in the same sentence as 7 diseases in open-access papers, as found by Europe PMC text mining. Sharing a sentence is not in itself a finding about the gene and the disease. The quoted sentences say what the papers report.
diabetes (1 paper, 2020). "In addition, Mfsd1 and Mfsd3 (presently called Slc33a2), Mfsd5 (now under the name of Slc61a1) and Mfsd11, Mfsd14a and Mfsd14b, and Unc93a are all affected by energy availability mice in vivo and Mfsd9 is linked to diabetes." (PMID 32733888, 2020).
SLC33A2 also shares sentences with these, for which no sentence is quoted: bladder cancer (1 paper); endometrial cancer (1); gastric cancer (1); head and neck cancer (1); hearing loss (1); ovarian carcinoma (1).